BCL2 (BCL2 apoptosis regulator)
Diseases named in the same sentence as BCL2 in open-access papers (continued):
Sharing a sentence is not in itself a finding about the gene and the disease.
colon carcinoma (continued). "Compared with normal colon cancer cells, ropivacaine could up-regulate the expression of Bax, caspase-3, a-caspase-3, caspase-9, a-caspase-9, and down-regulate the expression of bcl-2." (PMID 33345684, 2021). "BCL2 mRNA was the most stable among the 55 mRNAs analyzed in human colon cancer cells." (PMID 33723275, 2021). "Aloe-emodin-induced the apoptosis of colon cancer cells may occur by activating the mitochondrial pathway, upregulating caspase-3, caspase-9, and Bax, and downregulating the expression of Bcl-2, which may provide new ideas for future drug development." (PMID 33902610, 2021). "In human colon cancer HT-29 and LoVo cells, genistein could stimulate apoptosis by downregulating the NF-κB pathway and Bcl-2 while upregulating Bax; therefore, it provides the basis for genistein clinical application in colon cancer cases." (PMID 34336089, 2021). "miR-192-5p decreased the liver metastasis of colon cancer in an orthotopic mouse model of colon cancer through targeting the expression of several oncogenic genes, including anti-apoptotic BCL2, Wnt/β-catenin activator called zinc finger E-box binding homeobox 2 (ZEB2) and pro-angiogenic VEGFA." (PMID 32610706, 2020). "Curiously, this influence of miR-15a in BCL-2 levels was also demonstrated in colon cancer." (PMID 31967981, 2020). "Numerous other molecular mechanisms were suggested for the pro-apoptotic effect of SF, such as the cleavage of caspase-8 in pancreatic cancer, the fragmentation of the DNA-repairing protein poly (ADP-ribose) polymerase (PARP) and decreased expression of BCL2 in mammary, prostate and colon cancers." (PMID 32773768, 2020). "It was reported that DAPs demonstrated anti-cancer effect through induction of apoptosis in various human colon cancer cell lines involving activation of caspase-3 and down-regulation of anti-apoptotic Bcl-2 protein even at a very low concentration between the range of 2.5–6.0 μM." (PMID 32825505, 2020). "On the other hand, decrease of Bcl-2 protein level was observed in MS13-treated colon cancer cells." (PMID 32825505, 2020). "Previous studies have reported that IQ induces apoptosis via death receptor-mediated extrinsic pathway activation and the downregulation of anti-apoptotic proteins such as Bcl-2 and Bcl-xL, which are related to mitochondria-mediated apoptosis in colon cancer cells." (PMID 32825464, 2020). "Moreover, decline of BAX/BCL-2 ratio results in resistance to apoptosis[32 ▶], and reduced expression ratio of BAX/BCL-2 genes in colon cancer causes apoptosis resistance[32 ▶]." (PMID 32429645, 2020). "In this study we observed that WCAF had a certain trend of inhibiting the expression of BCL-2 in colon cancer, which could be further studied in the future." (PMID 33746736, 2020). "Moreover, the Bcl2-mediated inhibition of apoptosis restores the tumorigenicity of spontaneously regressive colon tumors in vivo." (PMID 32230772, 2020). "Furthermore, A1874-induced degradation of BRD4 protein and downregulated BRD-dependent genes (c-Myc, Bcl-2, and cyclin D1) in colon cancer cells." (PMID 32978368, 2020). "In Caco-2 colon cancer cells, MA treatment activated the extrinsic apoptotic pathway by inducing the cleavage of caspase-8 and caspase-3, increasing the levels of t-Bid, and decreasing the level of Bcl-2." (PMID 32998255, 2020). "In addition, LIN28B promotes the proliferation, colony formation and tumourigenesis of colon cancer cells by increasing BCL-2 expression." (PMID 32828126, 2020).
colon carcinoma (continued). "Furthermore, mRNA and protein expression of BRD4-dependent genes, including c-Myc, Bcl-2, and cyclin D1, was significantly decreased in A1874-treated colon cancer cells." (PMID 32978368, 2020). "Collectively, we develop a multifunctional nanoparticle formulation of afatinib and miR-139 with targeting, penetrating, and pH-responsive characteristics for simultaneous modulation of EGFR/HER/Ras/Akt/Rac1/STAT3/MAPK/EMT/Bcl-2 pathways to increase the sensitivity of colon cancer cells to afatinib." (PMID 31426807, 2019). "Overexpressed Tra2β could increase Bcl-2 expression through competition with miR-204, facilitating colon cancer cell growth." (PMID 31311954, 2019). "Furthermore, low expression of miR-206 resulting in higher BCL-2 expression increased 5-fluorouracil (5-FU)-resistance in colon cancer." (PMID 31887997, 2019). "In addition, GS was found to inhibit NF-kB signaling in colon cancer cells by quelling the expression of its regulated gene products Bcl-2, cIAP-1, and survivin." (PMID 31581454, 2019). "An exogenous increase in the expression of this miRNA may induce apoptosis in colon cancer cells by silencing Bcl-2." (PMID 31825987, 2019). "Furthermore, we identified numerous CTS transcriptional signatures whose expression was significantly associated with prognosis in colon cancer, such as CEBPB, PPARGC1, STAT3, MTOR, BCL2, JAK2, and CDK1." (PMID 31186640, 2019). "Increased in the Bax expression may affect Bcl-2/Bax or Bcl-xL ratio thus favoring colon cancer cell towards apoptosis." (PMID 31108984, 2019). "In colon cancer cells, the authors found that transformer 2β (Tra2β), a splicing factor overexpressed in many cancer tissues, modulates the accessibility of the miR-204 binding site on BCL-2 3′ UTR by competitive binding, thus stabilizing BCL-2 mRNA." (PMID 29570632, 2018). "Finally, CD155 knockdown increased the expression ratio between Bax and Bcl‐2, resulting in a significant increase in colon cancer cell apoptosis." (PMID 28816021, 2018). "In addition, expression of the pro-apoptotic protein, BAX, was also induced by treatment with Mimic-1 in colon cancer cells while the expression of BCL2 was suppressed." (PMID 29507661, 2018). "In addition, the anti-apoptotic proteins Bcl-2 was also reduced after açaí treatment in animals with induced-cancer, in agreement with a study of human colon cancer cells in which the proapoptotic activities of polyphenolics from açaí were described." (PMID 29966007, 2018). "The previous study demonstrated that aloperine induced a G2/M-phase cell cycle arrest, and inhibited Janus kinase (JAK)/Signal transducer and activator of transcription 3 (Stat3), phosphatidylinositol 3-kinase/Akt, as well as Bcl-2, in a human colon cancer cell line." (PMID 29361731, 2018). "In addition, studies have indicated that AKT signaling acts has a crucial role in colon cancer cell survival by modulating BCl2 and Bad." (PMID 29523145, 2018). "We stained paraffin sections from colon cancer biopsies of three individuals with antibodies against Aconitase 2 as a reporter of mitochondrial mass and, simultaneously, against one of the proteins Bax, Bcl-2, Bid, Mcl-1, Smac, XIAP, Casp8 and Bar." (PMID 29374163, 2018). "The correlation of GRα and bcl-2 in human colon cancer was explored." (PMID 28978062, 2017). "In a previous study, we described how MA triggered the intrinsic apoptotic process in HT29 colon-cancer cells, mediated by the participation of the Bcl-2 protein group, mitochondrial membrane disturbance, cytochrome-c release and the activation of caspases -9 and -3." (PMID 26751572, 2016).
colon carcinoma (continued). "BG-4 at 125 μg/mL significantly modified the expression of different apoptotic markers in HCT-116 colon cancer cells by increasing the expression of Bax and caspase-3 by 1.3-fold and 2.2-fold, respectively and decreasing the protein expression of Bcl-2 and XIAP by 44.3% and 67.0%, respectively." (PMID 27628414, 2016). "In this study, we analyzed L3 expression profile in colon cancer tissues and demonstrated that L3 mRNA amount decreased with malignant progression and the intensity of its expression was inversely related to tumor grade and Bcl-2/Bax ratio." (PMID 27835895, 2016). "In conclusion, this present study revealed that the isolated sulfated polysaccharides (PCP and/or PPP2) consisted of plentiful fucose and sulfated group contents have anticancer effects against CT26 colon carcinoma cells via regulation of the Bcl-2/Bax signal pathway." (PMID 26417363, 2015). "Previous investigations have reported that lunasin could induce the apoptosis of human colon cancer cells through the activation of mitochondrial pathway by upregulating Bax expression, decreasing Bcl-2 expression and promoting the activation of caspase-3." (PMID 25692134, 2015). "Studies in T-ALL and colon cancer cells have indicated that MEF2C may inhibit BCL2-regulated apoptosis and can function as a regulator of cell proliferation." (PMID 26487643, 2015). "Furthermore, these findings were verified by ChIP assays, which clearly demonstrated that MATα2 interacts with Bcl-2 P2 promoter in cells and in human colon cancer samples." (PMID 26416353, 2015). "This insight into the molecular mechanisms of the solution indicated that the LBF solution may significantly increase caspase 3 expression with a markedly reduced expression of Bcl-2, a potent anti-apoptotic protein, in colon cancer SW620 cells." (PMID 24765211, 2014). "Deletion of BCL2 leads to an increase in the relapse of stage II colon cancers and could be a likely biomarker for therapeutic decisions." (PMID 24943349, 2014). "However, the expression of Bcl2, Mcl-1, Survivin and Bclxl decreased significantly in all three colon cancer cell lines when treated with the combination of oxaliplatin and dovitinib." (PMID 24495750, 2014). "In conclusion, osthole-induced human colon cancer cell death may mediate by ROS generation, which subsequently induces Bax/Bcl-2 turnover and promotes caspase-3 activation and PARP-1 cleavage, resulting in cell apoptosis." (PMID 25013761, 2014). "It has been reported ethanol extracts from Actinidia chinensis may inhibit colon carcinoma LoVo cells and HT-29 cells proliferation, and induce apoptosis in LoVo cells accompanied by Bcl-2/Bax downregulation and Caspase-3 upregulation." (PMID 23758730, 2013). "Colon cancer cell growth inhibition was accompanied by downregulation of Sp1, Sp3 and Sp4 proteins and decreased expression of Sp-regulated gene products including bcl-2, survivin, VEGF, VEGFR1, cyclin D1, c-MET and p65 (NFκB)." (PMID 23110215, 2012). "Our results indicate that bufalin-induced colon cancer cell apoptosis is associated with the up-regulation of BAX, the down-regulation of livin and BCL-2, as well as the activation of caspase-3, indicating that bufalin induces apoptosis in different cells through different mechanisms." (PMID 23110625, 2012).
colon carcinoma (continued). "Consequently, the levels of mRNAs of HIF-1 target genes such as VEGF, MDR-1 and Bcl2 were significantly diminished by zinc in both cell lines, in agreement with our previous results on human colon cancer cells." (PMID 21179202, 2010). "Moreover,the results obtained on treating cell lines with PPAR ligands confirmobservations in colon cancer: there is an inverse correlation betweenPPARα and Bcl-2 and between PPARγ and c-Myc." (PMID 17389773, 2007). "Moreover, in colon cancer, the pathway of AKT/Bcl-2/BAX could promote the metastasis of colon cancer cells." (PMID 39074253, 2024). "In addition, FTGs activated the AMPK/mTOR autophagy pathway and downregulated the expression of JAK2/STAT3 apoptotic pathway proteins, while upregulated the expression of Bax and caspase-3 proteins and downregulated the expression of Bcl-2 proteins to exert an anti-colon cancer role." (PMID 38202610, 2023). "The anticancer effects of sericin were found to be due to a reduction in Bcl-2, which is a regulatory factor that promotes or inhibits apoptosis, and increased activity of caspase-3, which is an active factor in the end process of apoptosis that stimulates the apoptosis of colon cancer cells." (PMID 36902381, 2023). "Therefore, the increased activity of Akt/bcl-2 in colon cancer cells may play a crucial role in promoting cell survival under conditions of high oxidative stress." (PMID 38027228, 2023). "Meanwhile, the BUB3 protein could also reverse the promotion effect of miR-664b-3p on the apoptosis of the HCT116 and DLD-1 while boosting the expression of Bcl-2 and inhibiting the production of Bax, caspase-3, and caspase-9 in colon cancer cells over-expressed of miR-664b-3p." (PMID 35156516, 2022). "Indeed, in human colon cancer cell lines and colorectal cancer-xenografted mice, sertraline demonstrated proapoptotic activity by mitogen-activated protein kinase cascade activation and Bcl-2 inhibition." (PMID 34299028, 2021). "Besides, studies on multiple human colon cancer cell lines indicated that DAPs induced apoptosis by activating caspase-3 activity and reducing Bcl-2 protein." (PMID 34366863, 2021). "MiR-206 by targeting Bcl-2 could decrease 5-FU resistance in colon cancer cells." (PMID 33954114, 2021). "Hence, we contend that exosomal miR-375 may suppress ESCC by inactivating the Bcl-2 signaling pathway, which has been previously identified in colon cancer." (PMID 32698859, 2020). "Therefore, in this study, MS13 might promote colon cancer cell apoptosis through the activation of caspase-3 and decrease of Bcl-2 protein level." (PMID 32825505, 2020). "The ethanol extract of H. diffusa Willd at 0.5–5 mg/ml could induce apoptosis via mitochondria-mediated apoptotic pathway by alteration of the ratio of Bcl-2/Bax with downregulating antiapoptotic Bcl-2, upregulating proapoptotic Bax, and activating caspases-3 and -9 in colon cancer HT-29 cells." (PMID 31354479, 2019). "It has been concluded that the BCL2/BAX expression ratio may be considered as prognostic factor in low grade urinary bladder cancer, and also loss of BCL2 expression can be a prognostic factor in recurrent colon cancer." (PMID 28948511, 2017). "In addition, shikonin-induced depolarization of the mitochondrial membrane potential and decreased expression of Bcl-2 or Bcl-xL were likewise recovered, indicating that ROS acted upstream of the mitochondria in shikonin-induced apoptosis in colon cancer cells." (PMID 29312593, 2017). "Our data indicated that generation of ROS, down-regulated expression of Bcl-2 and Bcl-xL, depolarization of the mitochondrial membrane potential and activation of the caspase cascade were components of the programmed event of shikonin-induced apoptosis in colon cancer cells." (PMID 29312593, 2017). "However, overexpression of Bcl-2 in human colon tumors could be a resistance factor to this kind of co-treatment." (PMID 26771233, 2016).
colon carcinoma (continued). "Interestingly, these results are in agreement with a previous study showing that C. lanceolata extract could induce apoptosis via increasing the Bax/Bcl-2 ratio and activation of caspase-3 in human colon tumor HT-29 cells." (PMID 26426041, 2015). "We next used the chromatin immunoprecipitation (ChIP) assay to confirm that MATα2 can bind to Bcl-2 P2 promoter region in endogenous chromatin configuration in living cells and examine whether this is increased in human colon cancer where MATα2 is overexpressed." (PMID 26416353, 2015). "In fact, the low level of arachidonic acid was accompanied by an increase in antiapoptotic protein Bcl-2 and by the reduction of proapototic proteins and PPARα, indicating a decreased susceptibility to apoptosis in colon cancer with respect to non-neoplastic mucosa." (PMID 19841681, 2009). "Furthermore, bcl-2/bcl-xL bispecific oligonucleotides significantly reduced Bcl-xL expression that leads to increased apoptosis and delayed tumour growth in a xenotransplantation model for colon cancer." (PMID 14520471, 2003). "Subsequent assays in human colon carcinoma (Caco-2) and lung adenocarcinoma (A549) cell lines showed that β-sitosterol suppressed TNF-α and BCL-2 by approximately 55%, whereas cassipourol displayed only modest inhibition (~20%)." (PMID 42288609, 2026). "Ginsenoside compound K, a natural product, induces an apoptosis cascade in human colon cancer cells by upregulating DR5, cleaved caspase-9 and -3 and downregulating BCL2 expression." (PMID 41465451, 2025). "In colon cancer (HCT 116) cells, aloe-emodin inhibits cancer cell proliferation and induces apoptosis via the mitochondria-mediated pathway, involving Bax/Bcl-2 modulation, Caspase activation, and cytochrome C release." (PMID 40490812, 2025). "Butyrate also inhibits STAT3 signaling, thus suppressing the expression of bcl-2, bcl-XL, c-myc, cyclin D1, and HIF-1, resulting in decreased cell proliferation and increased apoptosis in both hypoxia and in colon cancer." (PMID 40699627, 2025). "Various studies found the apoptotic effects of Sericin on human cancer cells, such as that utilizing human colon cancer cells (SW480) with Sericin led to induction of apoptosis, decreased cell viability, caspase-3 activity, and decreased Bcl-2 expression." (PMID 38287097, 2024). "Mechanistically, they acted by negatively regulating the BCL2 and TGF genes, making them a good oral delivery system for colon cancer immunotherapy." (PMID 38534354, 2024). "In colon cancer HCT116 cells, E1–E4 exhibited a greater effect on the dysregulation of apoptotic proteins Bax and Bcl-2 than in HeLa cells." (PMID 39463485, 2024). "It was found that the geranyl acetate at high concentrations exhibit anticancer activity against colon cancer via the downregulation of anti-apoptotic BCL-2 protein and upregulation of apoptotic BAX protein in the colon cancer cells." (PMID 39298035, 2024). "Among them, LL37 and FK-16 induced caspase-independent apoptosis of colon cancer cells by inducing the nuclear translocation of AIF and EndoG through the upregulation of Bax and Bak and the downregulation of Bcl-2." (PMID 38069041, 2023). "In another report, withaferin A inhibited the Notch signaling pathway and downregulated Akt/NF-ĸB/Bcl-2 and the expression of rapamycin signaling elements PS6K and p4E-BP1 in HCT-116, SW-480, and SW-620 colon cancer cells." (PMID 37259311, 2023).